CD4 (CD4 molecule)
Diseases named in the same sentence as CD4 in open-access papers (continued):
Sharing a sentence is not in itself a finding about the gene and the disease.
Arthritis (continued). "Using flow cytometry, granulocytes, macrophages, B lymphocytes and CD4+ and CD8+ T lymphocytes were increased in the joints of the CD11c-Flip-KO mice with arthritis compared with controls." (PMID 25963626, 2015). "The small size of the study group limited clinical correlations, but the frequencies of CD146+CD4+ T cells correlated with erythrocyte sedimentation rate (ESR; r2 = 0·17, P = 0·022 for all patients with arthritis)." (PMID 25113810, 2015). "CIHH pretreatment has a protective effect against collagen-induced arthritis in rat through down-regulation of HIF-1α and NF-κB, inhibition of inflammatory cytokines TNF-α and IL-17, and balance in CD4/CD8 and Th1/Th2 T lymphocytes." (PMID 25861246, 2015). "Both in the blood and synovial fluid of arthritis patients and in the blood of HDs, circulating CD146+CD4+ T cells were enriched for cytokine‐producing Th effector cells." (PMID 25113810, 2015). "In CIA mice, ThiaMet-G significantly aggravated the severity of arthritis clinically and histologically, and it also increased CD4 + IFN-γ + T cells and CD4 + IL-17+ T cells." (PMID 26370562, 2015). "Transferring CD4+CD25+ T cells from B29-immunized donors from both, differently pre-treated groups, resulted in a similar suppression of clinical symptoms of arthritis as compared with the transfer of CD4+CD25- control cells." (PMID 26107957, 2015). "Patients 1 and 4 presented with arthritis, which was treated as juvenile idiopathic arthritis before diagnosis of XLA; both patients had markedly inverted CD4+/CD8+ ratio." (PMID 24885015, 2014). "Thus, we determined the percent frequency of Th17 (CD4+IL-17+) and Treg (CD4+Foxp3+) cells in CD4+ T cells isolated from the spleen or the inguinal lymph nodes of CIA mice that were treated with or without varying modified allo-tDCs on day 21 following the onset of arthritis." (PMID 24204938, 2013). "In line with the results in DIO mice, GSPE treatment in arthritis mice also exhibited attenuated expressions of STAT3 activity (both pSTAT3Tyr705 and pSTAT3Ser727) in CD4+ T cells, whereas pSTAT5 activity in those cells was profoundly augmented." (PMID 24223854, 2013). "The involvement of effector T-cell subsets was investigated by treating mice with depleting mAbs against CD4 or CD8 24 hours prior to immunization and again 24 hours prior to induction of arthritis." (PMID 22676339, 2012). "We found significant increase in the ratio of CD4 + CD25 + Foxp3+ cells among CD4+ cells in TSA-treated group compared to control group, suggesting that Treg are involved in the prevention of arthritis in SKG mice with TSA." (PMID 21592365, 2011). "B cells are important APC for CD4+ Th cells, which are critical for both the induction and the effector phase of G6PI-induced arthritis." (PMID 21931827, 2011). "Because the arthritis progression was IL-23 dependent, we further examined the role of IL-23 on the formation of IL-17A and IFN-γ-producing CD4+ T cells in this process." (PMID 20017902, 2009). "To identify the dominant cytokines at the onset of antigen-induced arthritis (day 8), we established the CBA array system using spleen CD4+ T cells plus mitomycin-treated APCs cultured in GPI." (PMID 18534002, 2008). "CD4+CD25+ and CD4+CD25− MLN cells were isolated on day 23 after arthritis induction and cultured with HSP60 peptide 180-188 or media." (PMID 17183718, 2006). "Before the onset of clinical arthritis, an elevated percentage of CD134+ CD4+ T cells was found in the PLN, which drain the foot and ankle joints, and in the ILN, which drain the Mt immunization site." (PMID 15899047, 2005). "Arthritis is part of the autoimmune syndrome induced by transfer of CD25-depleted splenocytes into lymphopenic hosts, and CD4+CD25+ cells are protective in collagen-induced arthritis." (PMID 15743476, 2005).
Arthritis (continued). "Results from NR4A1-KO mice indicate that inflammatory Ly6Chigh monocytes contribute to a mouse model of arthritis; in NR4A wild-type mice, CsnB increases levels of CD4+, CD25+, and FOXP3+ Treg cells in the presence of Ly6Clow monocytes to inhibit progression of arthritis." (PMID 40871737, 2025). "Furthermore, PIC suppressed the activation and polarization of CD4+ T cells, resulting in a decreased proportion of Th1 and Th17 cells (p < 0.001), ultimately improving the symptoms of CFA-induced arthritis in comparison to the model group." (PMID 40332204, 2025). "In our study, deleting Id2 resulted in a limited incidence and disease score of arthritis but did not completely eliminate the induction of CIA in Id2fl/fl Cd4‐Cre+ mice." (PMID 40051059, 2025). "Furthermore, these Sag-reactive CD4+ T cells expanded within arthritic joints of SKG mice, potentially driving arthritis." (PMID 39589811, 2024). "For three individuals (out of seven), it was not possible to detect cit-TNC-specific CD4+T cells at arthritis onset." (PMID 39557489, 2024). "To understand the transcriptional profile of these SKGNur GFPhi cells, we performed bulk RNA-Seq on naive (CD62LhiCD44loCD25–) CD4+ T cells with the highest (GFPhi) and lowest (GFPlo) GFP expression; these cells were obtained from SKGNur and WT (WTNur) mice before arthritis onset." (PMID 39589811, 2024). "This study determined whether D2R expressed on CD4+ T cells regulates inflammatory responses and signs in collagen type II (CII)-induced arthritis (CIA), a mouse model of RA." (PMID 37237413, 2023). "Our studies here did not reveal any significant changes in total CD4+ T cell numbers within the colonic lamina propria of mice with established arthritis, suggesting maintained barrier leakiness in established disease in the absence of intestinal inflammation." (PMID 36520064, 2023). "Similarly, in murine collagenase-induced arthritis, UCN administration can drive in vivo expansion of CD4+CD25+ Tregs in both lymph nodes and within joints." (PMID 37860766, 2023). "We found that ankle thickness and arthritis score were significantly decreased in mice injected with mTAp63KD retrovirus–infected SKG CD4+ T cells compared with those with nonsilencing retrovirus–infected SKG CD4+ T cells." (PMID 37212280, 2023). "TAC1 was not correlated with the immune cell content in cluster B arthritis patients, and resting memory CD4 T cells and activated NK cells were not correlated with the gene signatures." (PMID 35734177, 2022). "Proportions of IFNγ+ IL-17− CD4+ T (Th1) cells were similar between the two groups, whereas IFNγ− IL-17+ CD4+ T (Th17) cells were enriched in the combined ICI arthritis group (% within CD4+ T cells; PD-1 inhibitor arthritis vs. combined ICI arthritis; 0.79 ± 0.83 vs. 1.89 ± 0.64; P = 0.04)." (PMID 35413951, 2022). "Hence, high frequency of TNF-α+CD4+ and TNF-α+CD8+ T cells existed, probably contributing to the pathogenesis of severe arthritis and pneumonitis in the collagen antibody-injected and ICI-treated humanized BALB/c-hPD1/hCTLA4 mice." (PMID 36016934, 2022). "A recent study has shown that oral co-administration of HSP 65 and L. lactis in CIA mouse model ameliorated clinical and histological signs of arthritis, reduced inflammatory cytokines (IFN-γ and IL-17), as well as increased CD4+Foxp3+Tregs and CD4+LAP+ T cells." (PMID 36248797, 2022). "We found that SDMCs were highly accumulated in the spleen of arthritis-established SKG mice and could promote the polarization of CD4+ T cells toward Th1 and Tfh cells." (PMID 33643317, 2021). "We found that Clec4b limited the activation of arthritogenic CD4+αβT cells and the absence of Clec4b allowed development of arthritis already 5 days after adjuvant injection." (PMID 32497089, 2020).
Arthritis (continued). "As others have found, we show here a physiological increase in the frequency of CD4+CD25+FoxP3+ Tregs in blood, spleen and lymph nodes during the natural course of S. aureus arthritis, which is most likely due to the host’s regulation of the evoked immune response." (PMID 32111171, 2020). "Interestingly, we observed increased frequencies of Th1 (CD4+IFNγ+) and Th17 (CD4+IL-17+) cells in the small intestine and colon of CIA mice during the initiation phase of arthritis." (PMID 32332732, 2020). "Since we detected both IL‐23R(GFP)+ γδ T cells and IL‐23R(GFP)+CD4+CCR6+ T cells in the inflamed joints of mice, we aimed to investigate which of these cells are important for the progression of IL‐23R‐dependent arthritis." (PMID 31778214, 2020). "Surprisingly, no expansion of CD4+CD25+ T cells was observed within the first 6 days after arthritis induction." (PMID 32497089, 2020). "Additionally, triptolide influenced CD4+ and CD8+ cells distribution in Peyer's patch of DA rats with collagen induced arthritis." (PMID 32849899, 2020). "Although we cannot rule out that additional differences might occur at earlier times, this colonic CD4+ T cell phenotype was consistent with the one observed in prearthritic SKG mice and after induction of mannan-induced SKG arthritis." (PMID 33055428, 2020). "Of notice, numbers of total T cells (TCRβ+ cells) and CD4+ T cells and of total cTregs and RORγt-expressing cTregs — but not of CD4+IL-17+FoxP3– (cTh17) cells — were expanded in the colons of mice with established versus early DSS-induced arthritis." (PMID 33055428, 2020). "Whereas, neither CD4+CD25+Foxp3+Helios+ nor CCR6+ response to α-glucosidase inhibitors was observed in the groups when treatment started at arthritis induction." (PMID 32116681, 2019). "Thus, combined treatment with rapamycin and DON additively ameliorated the arthritis in SKG mice, possibly by suppressing CD4+ T cell proliferation and Th17 differentiation." (PMID 31011190, 2019). "This is consistent with an earlier report showing that AHR in CD4 T cells, but not in other immune cells, is important for arthritis development and Th17 expansion." (PMID 29884199, 2018). "We hypothesized that these B cells from CIA mice (CIA-B cells) interact with self-reactive CD4+ T cells in a specific manner in CIA, which may enhance the inflammatory reactions in arthritis." (PMID 29370826, 2018). "In contrast, not only Csf2−/− SKG CD4+ T cells but also WT SKG CD4+ T cells completely failed to induce arthritis macroscopically and histologically in Csf2−/−Rag2−/− mice." (PMID 29802020, 2018). "Reduced OX40 signals by MTX or Dex treatment may suppress the autoactivation of CD4+CD28− T cells and lead to arthritis remission." (PMID 28320444, 2017). "In the spleen, 3 days post arthritis induction, the mean percentage of CD4+ cells did not vary between MSC, CM-MSC and SFM control treatments (9.83 ± 1.54%, 11.36 ± 1.60%, 10.30 ± 1.60% respectively)." (PMID 29269885, 2017). "On one hand, this meant that, in early arthritis, additional mechanisms were involved in activation of CD4+CD28− T cells, except for OX40 costimulation, On the other hand, long-lived memory characteristics of OX40 may take effects in late arthritis." (PMID 28320444, 2017). "In contrast, depletion of CD8+ T cells, but not CD4+ T cells, decreased arthritis severity scores to similar levels as WT mice." (PMID 27857714, 2016). "Arthritis was also suppressed in mice recipient of CD4+ cells isolated from RORγt Tg mice only, but not from C57BL/6 mice." (PMID 25928901, 2015). "Although the data presented above point to a CD4+ T cell–independent effect of abatacept in the treatment of arthritis, they do not show such effects in a conclusive manner for CD4+ T cells returned after initial depletion." (PMID 26290328, 2015).
Arthritis (continued). "We report a decrease in disease progression and activity after abatacept treatment in the absence of CD4+ T cells, indicating that the mode of action of abatacept in established arthritis does not depend entirely on its effects on CD4+ T cell activation." (PMID 26290328, 2015). "In contrast, CD4 depletion only did not significantly alter arthritis development compared with the control group." (PMID 26290328, 2015). "Indeed, 1-MT abrogated the increase in the proportion of CD4+CD25+ Foxp3+ T cells induced by CD11b+ DC from EGCG-fed CIA mice which correlated with arthritis scores." (PMID 26379475, 2015). "We found that scid/scid mice that received transfer of whole-Il1rn−/− T cells or a mixture of γδ and CD4+ T cells developed arthritis, whereas those that received transfer of γδ or CD4+ T cells alone did not." (PMID 26108163, 2015). "However, the repertoires involved in human arthritis are predicted to be more clonal, based on heteroduplex TCR analysis in isolated CD4/CD8 T cells." (PMID 26561546, 2015). "In CFA-induced arthritis antigen-specific activated, but not resting CD4+ T lymphocytes are responsible for the spontaneous relief of inflammation-induced pain following Ag challenge." (PMID 24499354, 2014). "Additionally, in keeping with constitutive and universal expression of IL-10R2 there is similar levels of expression of this subunit in CD4+, CD11c+ and CD19+ cells from various phases of arthritis." (PMID 24676270, 2014). "All these results clearly indicate that neutrophils but not CD4+ T cells are the major source of IL-17 in the effector phase and affect the severity of arthritis." (PMID 23671588, 2013). "There were no statistical differences in arthritis severity between the recipients of IL-17KO and WT CD4+ T cells." (PMID 23671588, 2013). "This suggested that those CD4+CD25+ T lymphocytes which developed in the absence of IL-17-mediated inflammation conferred protection against the induction of arthritis." (PMID 22461836, 2012). "Late during the course of arthritis (day 42) the proportion of CD19+ MHCII+ B cells was decreased in lymph nodes in LNT-IL-10 mice whereas the proportion of CD4+ Foxp3+ regulatory T cells was not affected." (PMID 23166758, 2012). "We demonstrate that DTH-arthritis could be induced in C57BL/6 mice with paw swelling lasting for at least 28 days and that disease induction was dependent on CD4+ cells." (PMID 22676339, 2012). "We demonstrated previously that the Th17 subset of CD4+ T cells played a central role in the pathogenesis of GPI-induced arthritis; GPI-specific CD4+ T cells were skewed to TH-17 at the time of onset, and blockade of IL-17 resulted in a significant amelioration of arthritis." (PMID 19900268, 2009). "The results showed that many hGPI325-339-specific CD4+ T cells employed Vβ8.1 8.2 as the TCR repertoire, and co-immunization with APL (N329S, N329T, G332A, or G332V) significantly inhibited the development of arthritis." (PMID 19900268, 2009). "Transfer of CD4+CD25+ cells into immunized mice at the time of induction of antigen-induced arthritis decreased the severity of disease but was not able to cure established arthritis." (PMID 15743476, 2005). "Furthermore, post-treatment analysis of RA showed a decrease in CX3CR1+CD4+ T cells along with an improvement in arthritis, whereas no significant changes were observed in CX3CR1+CD8+ T cells." (PMID 39910629, 2025). "The baseline CD4+T cell phenotype was similar between individuals who progressed to arthritis (ie, in the pre-RA phase) and the non-progressors, when studying markers associated with Th1, Th17, T-peripheral and T-regulatory cells as well as with T-cell activation." (PMID 39557489, 2024). "A mouse model for post-CHIKV arthritis was used to test the effects of recombinant IL2 (rIL2), an anti-IL2 monoclonal antibody (mAb), and the complex on tarsal joint inflammation, peripheral IL2 levels, Tregs, CD4 + effector T cells (Teff), and histological disease scoring." (PMID 37147383, 2023).
Arthritis (continued). "Proinflammatory cytokine gene expression and CD4+ T cell infiltration in the brain were also increased with SL15649 infection, suggesting that like other encephalitic alphaviruses and with CHIKV-induced arthritis, the immune response contributes to CHIKV-induced neurological disease." (PMID 37243143, 2023). "In addition, Nur77 protein expression in CD4 T cells obtained from the RA joints far exceeded that in CD4 T cells isolated from synovial tissue of patients with a nonautoimmune form of arthritis." (PMID 34923645, 2022). "We also evaluated the onset and severity of arthritis induced by the adoptive transfer of CD4+ T cells from WT or Gsdmd−/−SKG mice into Rag2−/− or Gsdmd−/−Rag2−/− mice, which enables us to dissect the specific role of Gsdmd in CD4+ T cells and non-CD4+ T cells in recipient mice, separately." (PMID 34548542, 2021). "We adoptively transferred into Rag2-KO mice CD45.1-marked EGFP+ Tregs (CD4+FoxP3EGFP+) isolated from either the spleens or colons of FoxP3EGFP SKG mice together with CD45.2-marked SKG CD4+ effector (CD4+CD25–) peripheral T cells and monitored development of arthritis after injection of mannan." (PMID 33055428, 2020). "Importantly, without CD4 cells, no arthritis occurred, and the CD4+ T cells were responsible for inducing C-C motif chemokine ligand (CCL) 2 in the joints, that attracted the pathogenic γδ T cells." (PMID 32085540, 2020). "On day 13 after pristane injection, mRNA expression of Il17 and the Th17-associated cytokine, Il22, was approximately 60–80-fold higher in CD4+ T cells from inguinal than mesenteric LNs, which drains the intestine but not the joints, and whose T cells do not transfer arthritis." (PMID 32345366, 2020). "Notably, the percentage of CD4+ T cells expressing FoxP3 was not significantly correlated with arthritis score or significantly increased with TRI MP treatment." (PMID 32966314, 2020). "Also, in the spleen and inguinal LNs, which drain from the site of immunization, the percentage of IL‐23R(GFP) expressing CD4+CCR6+ T cells was increased during arthritis compared to naïve condition (data not shown)." (PMID 31778214, 2020). "In addition to and in agreement with a previous study, CD4+ T cell depletion neither had an impact on progression of arthritis (not shown) nor on pathogen load." (PMID 32613944, 2020). "Although CD4+ T cells represent only a minor population of the synovial infiltrate, they were shown to display a highly restricted TCR repertoire and limited clonality and their expansion correlated with onset and severity of arthritis as well as with anti-CII antibody levels." (PMID 30837986, 2019). "Our results demonstrated that the severity of arthritis was improved by suppressing serum inflammatory cytokines and the synovium cytokine mRNA expressions (especially those of IL-18, IFN-γ, TNF, and IL-6) and by suppressing the accumulation of CD4+ T cells in IL-18Rα KO mice." (PMID 31861496, 2019). "In our independent cohort of 161 treatment-naïve early arthritis clinic attendees, significant differences in normalized expression were seen for 11 of the 12 previously identified signature genes between RA and non-RA CD4+ T cells." (PMID 30753680, 2019). "GzmA secretion by Th1 CD4 T cells is thus unlikely to be a major driver of CHIKV arthritis." (PMID 31993061, 2019). "In contrast to the induction of CD4+ Tregs by Bregs52, which is impaired in the absence of IL-10+ B cells, here, we show that the differentiation of iNKT cells that limit inflammation in arthritis is CD1d-dependent but IL-10-independent." (PMID 29449556, 2018). "However, how depletion of CD4+ or CD8+ cells, both of which are expressed on some NKT cell subsets, could reduce B. burgdorferi tissue loads and increase arthritis severity in the TLR2−/− mice is unclear." (PMID 27857714, 2016).